TFAP2C (transcription factor AP-2 gamma)
Diseases named in the same sentence as TFAP2C in open-access papers (continued):
Sharing a sentence is not in itself a finding about the gene and the disease.
tumor (53 papers, 2012 to 2026). "We further identified prognosis-associated cell-type-specific and shared mpTFs, including TFAP2C, which was associated with stabilized fibroblast and monocyte functional states and a less aggressive tumor microenvironment phenotype." (PMID 42196406, 2026). "Previous studies showed that TFAP2C can promote tumor progression and is associated with poor prognosis in breast and lung cancers." (PMID 38123589, 2023). "The loss of TFAP2C limits the mitogenic response to estrogen and estrogen-induced tumor proliferation." (PMID 37291585, 2023). "Tumor susceptibility seems at least in part to be mediated by the TFAP2C target gene Nanos3 since Nanos3 heterozygous mice also develop GCC." (PMID 23967156, 2013). "Indeed, the association between increased TFAP2A and TFAP2C expression was observed in both the TCGA BC cohort, as well as our in-house tumor cohort." (PMID 31772149, 2019). "Because of the close association between TFAP2A and TFAP2C expression and the aggressive basal-squamous subtype, as well as their association with lymph node metastasis and distant recurrence in our tumor cohort, we hypothesized these transcriptional regulators may promote disease aggressiveness." (PMID 31772149, 2019). "GSEA was further performed and the results showed that TFAP2C expression level was positively associated with the YAP and TAZ-activated gene signatures, suggesting that the inactivation of Hippo signaling pathway may be associated with the pro-tumor effects of TFAP2C." (PMID 29439714, 2018). "This upregulation of TFAP2C in cancer samples suggests its potential involvement in tumor progression." (PMID 40541807, 2025). "This study identified key transcription factors, such as TFAP2C, POU5F1, SOX17, and NANOG, which play critical roles in tumorigenesis, and demonstrated that TFAP2C promotes tumor migration and invasion." (PMID 40362187, 2025). "TFAP2C regulates genes involved in cell cycle progression and epithelial–mesenchymal transition, contributing to tumor aggressiveness." (PMID 40541807, 2025). "In the xenograft model, TFAP2C silencing significantly inhibited tumor growth and reduced cisplatin resistance." (PMID 40541807, 2025). "In vivo, silencing TFAP2C in a cisplatin-resistant BC xenograft model resulted in significantly reduced tumor growth and decreased expression of YAP and β-catenin." (PMID 40541807, 2025). "According to the experimental results, the tumors in the cisplatin-resistant group were significantly larger compared to those in the cisplatin-sensitive group, while tumor growth was markedly slowed in the TFAP2C-silenced cisplatin-resistant group." (PMID 40541807, 2025). "In recent years, studies on TFAP2C have found that it has similar DNA binding sites, similar anti-tumor effects and mechanisms with TFAP2A." (PMID 37859819, 2023). "For instance, the expression of the AP-2γ transcription factor (TFAP2C), a miR-214 direct target, was found reduced by Western Blot (WB) analysis following tumor cell treatments with miR-214over EVs." (PMID 36639824, 2023). "We observed tumor migration and invasion were both significantly decreased in the TFAP2C knockdown group." (PMID 38123589, 2023). "Previous studies have shown that TFAP2A and TFAP2C have inhibitory effects on tumor growth in a variety of tumors 6-8." (PMID 37859819, 2023). "The present study confirmed that TFAP2C knockdown enhanced the anti-tumor effects of cisplatin by decreasing cisplatin-induced activation levels of epidermal growth factor receptor (EGFR) and nuclear factor kappaB (NF-κB)." (PMID 36230734, 2022). "We showed that TFAP2C knockdown enhanced the anti-tumor effects of cisplatin in vivo and in vitro by reducing the levels of EGFR and NF-κB activation, thereby providing a new idea for improving the efficacy of cisplatin." (PMID 36230734, 2022).
tumor (continued). "The results indicated that the expression of TFAP2C was significantly different in tumor tissues compared to the corresponding normal tissues in 19 different cancers." (PMID 36230734, 2022). "To show the expression of TFAP2C in human BCa more clearly, we compared TFAP2C mRNA levels between tumor tissues (n = 407) and normal tissues (n = 28) using the UCSC Xena database (for GTEx-bladder and TCGA-BLCA data)." (PMID 36230734, 2022). "Multifactor ANOVA results showed TFAP2C knockdown and cisplatin treatment had a synergistic effect on tumor suppression." (PMID 36230734, 2022). "It has been shown that the interplay of WWOX and TFAP2A/TFAP2C affects the biology of the tumor thus corresponding bioinformatics analyses involving BLCA cohort were performed as a follow-up of in vitro experiments." (PMID 33691672, 2021). "TFAP2C upregulates the GPX4 gene in tumor cells and regulates some ferroptosis regulators, such as epidermal growth factor receptor (EGFR), CDKN1A, and YAP1, thereby negatively regulating ferroptosis." (PMID 34804126, 2021). "Further, ZR75‐PELP1 KD + TFAP2C xenografts displayed significantly reduced tumor volumes compared with ZR75‐TFAP2C xenografts." (PMID 33269540, 2021). "The results showed that the expression of HAMP, FDFT1, GDF15, TFAP2C all increased in tumor tissues, indicating their meaningful regulatory roles in CRC." (PMID 34249766, 2021). "Oncogenic miRNA-10a-5p directly regulates multiple tumor-suppressive genes, namely transcription factor AP-2 gamma (TFAP2C), phosphatase and tensin homolog (PTEN) and cell adhesion molecule L1 like (CHL1)." (PMID 32756339, 2020). "In consistence with previous report in which knockdown of TFAP2C decreased the number of cells in S phase and delayed the growth of xenograft tumor in both E2− and E2 + conditions, we observed a reduction of cell viability in all six AFF4-knockout lines." (PMID 32265480, 2020). "In this study, both WEE1 and BRCA1 were found to be up‐regulated by enhanced TFAP2C mRNA stability and they drove tumour growth in vivo." (PMID 32857912, 2020). "Taken together, the results suggest that GADD45B and PMAIP1, when negatively regulated by TFAP2C, can act as tumor suppressive factors inhibiting NSCLC tumorigenesis." (PMID 31296259, 2019). "In luminal breast cancer, TFAP2C increases epidermal growth factor receptor expression, resulting in cancer cell proliferation and tumor growth." (PMID 31296259, 2019). "Previous studies have revealed that microRNA-10b promotes the metastasis of a variety of tumor cells by regulating Bim, TFAP2C, P16, P21, E-cadherin, CD138, RHOC, RhoC, uPAR, MMP-2, MMP-9, HOXD10, etc 23-29." (PMID 31592231, 2019). "In this study, we analyzed microarray data to identify tumor suppressor genes and nine genes downregulated by TFAP2C were screened." (PMID 31296259, 2019). "Through an analysis of a TFAP2C-related microarray dataset, we identified nine candidate genes functioning as tumor suppressors." (PMID 31296259, 2019). "Our findings suggest PPARɣ inactivation, as well as TFAP2A and TFAP2C overexpression cooperate with other TFs to promote the basal-squamous transition during tumor progression." (PMID 31772149, 2019). "Studies of the Slug-mediated network have found that another tumor progression in NSCLC can be also be promoted by suppressing TFAP2C." (PMID 30824562, 2019). "In vivo tissue recombination studies show TFAP2A and TFAP2C promote tumor growth in line with the aggressive nature of basal-squamous bladder cancer." (PMID 31772149, 2019). "Both TFAP2A and TFAP2C hold distinct roles as oncogenes or tumor suppressors in various tumor models." (PMID 30824562, 2019). "Among the matched tumor-adjacent tissues, 35 presented with low TFAP2C expression, whereas 55 had high expression." (PMID 29615098, 2018). "The number of tumor initiating cells (TIC) required to develop tumor in mice were significantly reduced in the TFAP2C-overexpressing mice group, but enhanced in TFAP2C-silenced mice group." (PMID 29439714, 2018).
tumor (continued). "Meanwhile, TFAP2C acted as a tumor suppressor to decrease the PDAC cell migration and invasion capability and negatively modulated EMT-associated gene expression." (PMID 29615098, 2018). "The tumor volumes and weight were increased in the TFAP2C -overexpressing plus 5-FU mice group, but were dramatically decreased in the TFAP2C-silencing plus 5-FU mice group, compared to the corresponding mice controls." (PMID 29439714, 2018). "TFAP2C expression trended downward in PDAC tissues compared with tumor-adjacent tissues (P = 0.1147)." (PMID 29615098, 2018). "A mouse model evaluated the effects of TFAP2C silencing on tumor growth and cisplatin resistance." (PMID 40541807, 2025). "TFAP2C is also associated with the malignant phenotypes of ovarian and colorectal cancers by regulating genes linked to the cell cycle, apoptosis, and EMT, enhancing tumor growth and invasion." (PMID 40664662, 2025). "Moreover, TFAP2C interacts with other molecular pathways influencing tumor progression and drug resistance." (PMID 40541807, 2025). "We then examined the ability of migration and invasion of tumor cells upon TFAP2C knockdown." (PMID 38123589, 2023). "Therefore, an inhibited mitogenic response to estrogen treatment and decreased hormone-responsive tumor growth are observed when TFAP2C expression is downregulated." (PMID 37291585, 2023). "Among the TFAP2 family members, TFAP2A and TFAP2C are involved in regulating tumor stemness." (PMID 37291585, 2023). "Finally, Xenograft experiments demonstrated that TFAP2C knockdown also enhanced the anti-tumor effect of cisplatin in vivo." (PMID 36230734, 2022). "Interestingly, TFAP2C exhibits pro- and anti-tumor functions in different tumors, depending on the function and tumor type." (PMID 36230734, 2022). "Current studies have demonstrated that TFAP2C plays an important role in the regulation of cell proliferation, cell cycle progression and apoptosis, participating in the development of several cancers and influencing tumor sensitivity to chemotherapy." (PMID 36230734, 2022). "The increased expression of TFAP2C supported that TFAP2C has a pro-tumor function in BCa." (PMID 36230734, 2022). "Overexpression of TFAP2C was demonstrated to resensitize tumor cells to gemcitabine in PDAC." (PMID 34732701, 2021). "TFAP2C plays an essential role in cell differentiation, tissue development, and tumor biology." (PMID 34804126, 2021). "TFAP2C is scarcely detectable in normal tissues, and it reappears in a panel of tumours." (PMID 32857912, 2020). "The significance of TFAP2C in anti‐tumour treatment is depicted in several studies." (PMID 32857912, 2020). "A similar pathway, but with a different effect, could be observed in neuroblastoma: miR-200a directly targets TFAP2C, thus tumor growth and cell proliferation." (PMID 30824562, 2019). "However, T24 tumor xenograft volume was significantly increased following expression of TFAP2C (p < 0.01; quantified in 8j) 2 months following implantation." (PMID 31772149, 2019). "A similar approach was used to investigate the regulation and role of EGFR in luminal BC where the knockdown of TFAP2C has induced decreased expression of EGFR in a panel of this tumor and, consistently, the EGFR gene has resulted by ChIP-seq to be a TFAP2C target." (PMID 35582269, 2019). "In addition, UMUC3-associated tumor xenograft volume was significantly increased following overexpression of TFAP2A (p < 0.05; quantified in 8k) and TFAP2C (p < 0.01; quantified in 8l)." (PMID 31772149, 2019). "However, overexpression of TFAP2C in NSCLC leads to excessive cell cycle activation which promotes tumor aggressiveness: the proposed model of action consists of simultaneous induction of oncogenic miR-183 and down-regulation of suppressive miR-33a." (PMID 30824562, 2019).
tumor (continued). "Furthermore, the activity of caspase-3 or − 9 in the tumor tissues from TFAP2C -overexpressing plus 5-FU mice group was robustly suppressed, but enhanced in the tumor tissues from TFAP2C -silencing plus 5-FU mice group." (PMID 29439714, 2018). "However, in our study results, TFAP2C works as a tumor suppressor and can suppress PDAC cell migration and invasion, as well as negatively regulate certain protein levels." (PMID 29615098, 2018). "In contrast, TFAP2C knockdown in T3M4 cells promoted tumor cell migration and invasion." (PMID 29615098, 2018). "Our results suggested that TFAP2C expression was primarily detected within the cytoplasm and nucleus, but occurred mostly in the nucleus, and its expression was higher than that in adjacent tissues (5 of 6 cases had higher expression in tumor tissues than in adjacent normal tissues)." (PMID 36230734, 2022). "Besides, high expression of TFAP2C is correlated with poor survival in certain types of tumours." (PMID 32857912, 2020). "Both TFAP2C and YAP mRNA levels were significantly elevated in tumor samples, and Western blot confirmed higher YAP and p-YAP protein levels in BC tissues." (PMID 40541807, 2025). "Through transcription factor analysis, we can see that State7, 6, 5, 3, representing tumours, is enriched in STAT5B, TFAP2C, KLF1, ZBTB7A, etc.." (PMID 38613345, 2024). "In contrast to TFAP2C, extensive research indicates that TFAP2A plays a significant tumor suppressive role in breast tissues, exhibiting functions crucial for growth suppression and maintenance of the differentiated state." (PMID 38890750, 2024). "Univariable analysis showed that age, molecular subtype, tumor TNM staging, TFAP2A, TFAP2B, TFAP2C and TFAP2E were important factors affecting the survival of BLCA patients." (PMID 37859819, 2023). "Posttranslational modifications also influence the tumor-promoting and tumor-suppressing functions of TFAP2A and TFAP2C during the EMT process." (PMID 37291585, 2023). "The subsequent in vivo experiments also showed that TFAP2C knockdown led to a decrease in cisplatin-induced EGFR levels and further inhibited tumor growth." (PMID 36230734, 2022). "Under cisplatin treatment conditions, TFAP2C knockdown led to lower levels of EGFR and NF-κB activation, enhancing the anti-tumor effect of cisplatin in BCa." (PMID 36230734, 2022). "Our study showed that TFAP2C knockdown affected the activation levels of EGFR and NF-κB and enhanced the anti-tumor effects of cisplatin in vivo and in vitro." (PMID 36230734, 2022). "Ki67 staining of the tumor sections revealed greater proliferation in the ZR75‐TFAP2C xenografts than in the ZR75 control and ZR‐75‐PELP1 KD + TFAP2C tumors." (PMID 33269540, 2021). "Our study is the first to investigate the roles of TFAP2C in PDAC and to elucidate the tumor suppresser role of this protein." (PMID 29615098, 2018). "We evaluated the TFAP2C expression levels in 90 PDAC tissue samples and matched tumor-adjacent tissues by IHC staining." (PMID 29615098, 2018). "We hypothesized that modifying the methylation state could restore TFAP2C and OTUD1 expression, thus enhancing tumor cell radiosensitivity." (PMID 40664662, 2025). "While the predominance of TFAP2C expression in ACC has been previously documented, our work represents the first evidence suggesting that TFAP2E may also play a role in this tumor type." (PMID 41373739, 2025). "In tumor models, both TFAP2A and TFAP2C are important to cell proliferation and migration." (PMID 38890750, 2024). "WWOX/TFAP2A demonstrates anti-tumor functions, while WWOX/TFAP2C still promotes oncogenesis." (PMID 37291585, 2023). "Interaction among TFAP2C, c-Myc and lysine demethylase 5B (KDM5B) can form a protein complex that promotes cell cycle progression by transcriptionally inhibiting P21 expression, consequently resulting in tumor growth." (PMID 37291585, 2023).
tumor (continued). "In NSCLC, LncRNA PP7080 promotes the phosphorylation of TFAP2C, which then upregulates the expression of programmed cell death protein 6 (PDCD6) to promote cancer cell malignancy and to induce immune-suppressive tumor microenvironment by recruiting myeloid-derived suppressor cells." (PMID 37291585, 2023). "Therefore, an in silico analysis was also performed on clinical data obtained from TCGA database since the tumor profile is changing globally in terms of WWOX and TFAP2C levels which corresponded to our research model." (PMID 33691672, 2021). "Moreover, our results demonstrated that TFAP2C promoted the chemoresistance and stemness of CRC cells in vitro and in vivo, further determining the tumor-stimulatory role of TFAP2C in CRC." (PMID 29439714, 2018). "Additionally, the tumor cells were positive for OCT3/4 and TFAP2C and negative for SOX2." (PMID 27283990, 2016).